PEX2 (peroxisomal biogenesis factor 2)
Description:
E3 ubiquitin-protein ligase component of a retrotranslocation channel required for peroxisome organization by mediating export of the PEX5 receptor from peroxisomes to the cytosol, thereby promoting PEX5 recycling. The retrotranslocation channel is composed of PEX2, PEX10 and PEX12; each subunit contributing transmembrane segments that coassemble into an open channel that specifically allows the passage of PEX5 through the peroxisomal membrane (By similarity). PEX2 also regulates peroxisome organization by acting as a E3 ubiquitin-protein ligase (By similarity). PEX2 ubiquitinates PEX5 during its passage through the retrotranslocation channel: catalyzes monoubiquitination of PEX5 at 'Cys-11', a modification that acts as a signal for PEX5 extraction into the cytosol (By similarity). Required for pexophagy in response to starvation by mediating ubiquitination of peroxisomal proteins, such as PEX5 and ABCD3/PMP70. Also involved in the response to reactive oxygen species (ROS) by mediating 'Lys-48'-linked polyubiquitination and subsequent degradation of PNPLA2/ATGL, thereby regulating lipolysis.
Synonyms: PAF-1; PAF1; PMP3; PMP35; PXMP3; RNF72; ZWS3; PBD5A; PBD5B
Tractability: Antibody: UniProt predicts a signal peptide or a membrane-spanning region. PROTAC: ubiquitination databases record sites on it; its protein half-life has been measured.
Target class: Enzyme; Transferase
Gene: Protein-coding gene on chromosome 8 (76,980,258 to 77,001,044, reverse strand). Ensembl gene ENSG00000164751.
Subcellular location: Peroxisome membrane
Subcellular location (Human Protein Atlas): Vesicles; Nucleoplasm
Pathways (Reactome):
Protein localization: Class I peroxisomal membrane protein import; Peroxisomal protein import
Metabolism of proteins: E3 ubiquitin ligases ubiquitinate target proteins
Gene Ontology:
Molecular function: protein binding; ubiquitin protein ligase activity; protein transmembrane transporter activity; zinc ion binding
Biological process: cellular response to reactive oxygen species; fatty acid beta-oxidation; negative regulation of epithelial cell proliferation; negative regulation of fibroblast proliferation; peroxisome organization; pexophagy; protein destabilization; protein import into peroxisome matrix; protein import into peroxisome matrix, receptor recycling; protein monoubiquitination; response to amino acid starvation; very long-chain fatty acid metabolic process; protein import into peroxisome matrix, substrate release; protein ubiquitination
Cellular component: Cdc73/Paf1 complex; membrane; peroxisomal membrane; ubiquitin ligase complex; cytosol; peroxisome
Genetic constraint (gnomAD): Loss-of-function variants: 19 observed, 26.36 expected, observed/expected ratio (o/e) 0.72, 90% interval 0.5 to 1.06. The upper end of that interval is the gene's LOEUF score, 1.06, which puts it in group 4 of 6, group 1 being the genes least tolerant of losing a copy. Missense variants: 347 observed, 369.82 expected, observed/expected ratio (o/e) 0.94, 90% interval 0.86 to 1.02. Synonymous variants: 141 observed, 135.58 expected, observed/expected ratio (o/e) 1.04, 90% interval 0.91 to 1.2.
Gene-disease validity (ClinGen):
ClinGen rates the evidence that PEX2 causes each of these diseases.
peroxisome biogenesis disorder (autosomal recessive): Definitive.
Homologues: Orthologues: chimpanzee PEX2 (99% identical), macaque PEX2 (98% identical), rabbit PEX2 (91% identical), dog PEX2 (90% identical), guinea pig PEX2 (89% identical), mouse Pex2 (88% identical), rat Pex2 (88% identical), pig PEX2 (85% identical), tropical clawed frog pex2 (66% identical), zebrafish pex2 (55% identical), Drosophila melanogaster Pex2 (25% identical), Caenorhabditis elegans prx-2 (20% identical).
Diseases named in the same sentence as PEX2 in open-access papers:
PEX2 is named in the same sentence as 41 diseases in open-access papers, as found by Europe PMC text mining. Sharing a sentence is not in itself a finding about the gene and the disease. The quoted sentences say what the papers report.
Zellweger syndrome (16 papers, 2008 to 2025). "Biallelic PEX2 variants cause Zellweger spectrum disorders, which frequently include hypotonia, liver dysfunction, developmental delay, and ocular abnormalities such as corneal opacities, retinal anomalies, and AC malformations." (PMID 40650233, 2025). "The phenotype of mice with Pex2, Pex5 and Pex13 deficiency resembles the severe form of human Zellweger syndrome." (PMID 26686055, 2016). "Currently, several mouse models of the Zellweger spectrum disorders are available, which are represented by mice with targeted deletions in the genes encoding the peroxins PEX2, PEX5 or PEX13." (PMID 26686055, 2016). "The protein products of both PEX1 and PEX2 are involved in peroxisome biogenesis and are implicated in a genetic disease associated craniofacial and skeletal abnormalities (Zellweger's syndrome)." (PMID 19557189, 2009). "Genetic deletion of Pex2, Pex5, or Pex13 in mice causes profound and global peroxisome deficiency, and is associated with growth delay, severe hypotonia, and death shortly after birth, similar to Zellweger syndrome in humans." (PMID 40949164, 2025). "Deficiency of the peroxisome assembly gene (PEX2) in mouse brain is a model of Zellweger syndrome." (PMID 33095273, 2021). "The clinical phenotype of these two patients strongly differs from PBD patients with PEX2 gene mutations who may display cerebellar symptoms in addition to other severe neurological signs in the context of Zellweger spectrum disorders." (PMID 21392394, 2011). "Mitochondrial abnormalities are found in patients with Zellweger syndrome and mouse models with deletion of Pex2 and Pex5, underscoring the role of peroxisomes in mitochondrial health." (PMID 37338571, 2023). "We observed a considerable decrease in KHK expression followed by ALDOB, both enzymes unique for fructose metabolism, on mRNA and protein levels in a Zellweger syndrome mouse model (Pex2–/– mice)." (PMID 32733884, 2020). "Mutant form of Pex2 is responsible for abnormal neuronal migration in Zellweger syndrome (peroxisome biogenesis disorder)." (PMID 25423262, 2014). "Mutations in human PEX2 cause Zellweger spectrum disorder but have no apparent impact on white matter appearance." (PMID 29251594, 2017). "Zellweger spectrum disorders (ZSDs), including archetypal Zellweger syndrome, neonatal adrenoleukodystrophy (NALD) and infantile Refsum disease (IRD), are PBDs caused by mutations in peroxin genes (PEX1, PEX2, PEX3, PEX5, PEX6, PEX10, PEX11β, PEX12, PEX13, PEX14, PEX16, PEX19 or PEX26)." (PMID 40949164, 2025). "We demonstrate a strong decrease in total KHK at the mRNA and protein level, which is also reflected in decreased expression of both the Khka and Khkc isoforms, in livers from the Pex2–/– mouse model for Zellweger syndrome without functional peroxisomes." (PMID 32733884, 2020).
peroxisome biogenesis disorder (9 papers, 2014 to 2025). "For peroxisomal biogenesis disorders, premature termination codon mutations in PEX2 and PEX12 have previously been analyzed showing improved metabolic activity after G418 treatment." (PMID 34356630, 2021). "Because PEX2 has been implicated in peroxisome biogenesis, and peroxisome biogenesis disorders (PBDs) are typically associated with impaired lipid metabolism and CNS myelin defects, this prompted us to further explore a potential link between LRP1 and peroxisomes." (PMID 29251594, 2017). "Another explanation for why no ER stress and UPR activation was observed in peroxisome-deficient CHO cells, in contrast to, e.g., postnatal Pex2–/– mouse tissues or biopsies obtained from patients with peroxisomal disorders, might be the lack of accumulation of ER stress-inducing metabolites." (PMID 33240873, 2020). "Of note, three of the four PEX proteins (PEX2, PEX7 and PEX13 targeted by HIV-induced miRNAs are associated with peroxisome biogenesis disorders." (PMID 28594894, 2017). "Consequently, plasma cholesterol levels are reduced both in patients with peroxisome biogenesis disorders and in 10-day-old Pex2–/– mice." (PMID 33240873, 2020). "In cells from patients with peroxisome biogenesis disorders, peroxisomes are absent due to mutations in one or more genes that encode critical biogenesis factors including PEX2, PEX7 and PEX13." (PMID 28594894, 2017). "In contrast to other peroxisomal biogenesis disorder (PBD) mouse models (such as the Pex5, Pex2, Pex13 knockout mice), which mimic the Zellweger spectrum symptoms, the Pex11a knockout mice still contain peroxisomes that harbor the typical peroxisomal marker enzymes." (PMID 41511296, 2025). "Therefore, it is critical to study PEX genes involved in different aspects of biogenesis, such as PEX2 and PEX16, when characterizing peroxisomal biogenesis disorders." (PMID 39605732, 2024).
hepatocellular carcinoma (3 papers, 2018 to 2021). A malignant tumor that arises from hepatocytes. "As previous publications observed an up-regulation of Pex2 at the mRNA level in hepatic carcinomas, Cai and colleagues silenced Pex2 by RNAi in hepatocellular carcinoma xenografts and reported significantly reduced tumor growth in response to the treatment." (PMID 30219925, 2018).
cholestasis (2 papers, 2020 to 2025). Impairment of the bile flow caused by obstruction within the liver, or outside the liver in the bile duct system. "Feeding Pex2–/– mice with bile acids (BA) improves intestinal lipid absorption, reduces cholestasis and accumulation of toxic bile acid intermediates and thus prolongs survival." (PMID 32733884, 2020). "In addition, the livers from PEX2 knockout mice showed aggravated steatosis and cholestasis during the first weeks of life." (PMID 40943222, 2025).
Hepatic steatosis (2 papers, 2023 to 2025). Steatosis is a term used to denote lipid accumulation within hepatocytes. "These mice developed hepatic steatosis similar to other models of loss of peroxisome function, such as in PEX2 and PEX5 deficiency." (PMID 37338571, 2023).
steatosis (2 papers, 2020 to 2021). Increased lipid within the cytoplasm of cells. "Pex2–/– mice are characterized by severe growth retardation, intestinal malabsorption, hepatic cholestasis and steatosis as well as dysregulated cholesterol homeostasis and ER stress." (PMID 32733884, 2020).
Alzheimer disease (1 paper, 2024). A progressive, neurodegenerative disease characterized by loss of function and death of nerve cells in several areas of the brain leading to loss of cognitive function such as memory and language. "PEX2, when highly expressed, exhibited an association with Alzheimer's disease, contrasting with its low expression group, which demonstrated an association with asthma." (PMID 38965390, 2024).
cyst (1 paper, 2011). A sac-like closed membranous structure that may be empty or contain fluid or amorphous material. "Interestingly, this finding was not comparable with the previously reported results that Drosophila pex2 in germ cells, but not in cyst cells, is required for germ-cell maturation." (PMID 21826223, 2011).
HIV-1 infection (1 paper, 2020). The type species of lentivirus and the etiologic agent of acquired immunodeficiency syndrome (AIDS). "Seventy-two hours later, the relative levels of four peroxisomal biogenesis factors (PEX2, PEX7, PEX11B, and PEX13) that are downregulated during HIV-1 infection of human cells were assessed by immunoblotting." (PMID 32127461, 2020).
intrahepatic cholestasis (1 paper, 2020). A cholestasis characterized by impairment of the bile flow caused by obstruction located in the liver. "Treating Pex2–/– mice with bile acids prolonged postnatal survival, alleviated intestinal malabsorption and intrahepatic cholestasis, and reduced production of toxic C27-bile acid intermediates." (PMID 32733884, 2020).
liver cancer (1 paper, 2025). An epithelial or non-epithelial malignant neoplasm that arises from the liver. "A recent investigation reveals that the inhibition of PEX2, a peroxin responsible for the degradation of peroxisomes through autophagy (known as pexophagy), decreased the rate of liver cancer tumor expansion." (PMID 40487257, 2025).
tumor (5 papers, 2016 to 2025). "A recent study reports that silencing PEX2, a peroxin involved in autophagosomal degradation of peroxisomes (pexophagy), reduced tumor growth in liver cancer." (PMID 33718356, 2021).
infection (3 papers, 2017 to 2021). The state of being infected such as from the introduction of a foreign agent such as serum, vaccine, antigenic substance or organism. "Infection with an isogenic Nef knockout virus had a similar effect on PEX2, PEX7, PEX13, and PEX11B as wild-type HIV-1." (PMID 32127461, 2020). "Immunoblotting revealed that infection of primary macrophages, a physiologically relevant cell type in HIV patients, resulted in dramatic loss of PEX2, PEX7, PEX13, and to a lesser extent, PEX11B." (PMID 28594894, 2017). "Unlike wild-type HIV-1, infection with Vpu-S52,56D and Vpu-S52,56N viruses did not result in a significant loss of PEX2, PEX7, PEX11B, or PEX13 in HeLa-CD4/CXCR4/CCR5 cells, macrophages, or T cells." (PMID 32127461, 2020). "In our study, two genes peroxin 2 (PEX2) and peroxin 13 (PEX13) were significantly down-regulated, which might affect peroxisomal protein import and thus fail to detoxify ROS at the infection site." (PMID 34072279, 2021).
neoplastic disorders (1 paper, 2025). "PEX2 and other peroxins—namely, PEX5, PEX10, and PEX12—play a pivotal role in ensuring the survival of malignant cells and, consequently, emerge as prospective therapeutic targets for combating neoplastic disorders." (PMID 40487257, 2025).
PEX2 also shares sentences with these, for which no sentence is quoted: Zellweger spectrum disorders (5 papers); developmental delay (2); liver dysfunction (2); adrenocortical carcinoma (1); asthma (1); Ataxia (1); autism (1); autosomal recessive cerebellar ataxia (1); Bardet-Biedl syndrome (1); Breast Invasive Carcinoma (1); cancer (1); genetic disease (1); Infertility (1); inflammatory bowel disease (1); Joubert syndrome (1); Leukoencephalopathy (1); metabolic disease (1); ovarian serous cystadenocarcinoma (1); primary ciliary dyskinesia (1); rectal adenocarcinoma (1); Refsum disease (1); sarcoma (1); schizophrenia (1); Seckel syndrome (1); uterine carcinosarcoma (1); Walker Warburg syndrome (1); X-linked adrenoleukodystrophy (1).